PRF1 (perforin 1)
Description:
Pore-forming protein that plays a key role in granzyme-mediated programmed cell death, and in defense against virus-infected or neoplastic cells. Plays an important role in killing other cells that are recognized as non-self by the immune system, e.g. in transplant rejection or some forms of autoimmune disease. Can insert into the membrane of target cells in its calcium-bound form, oligomerize and form large pores. Promotes cytolysis and apoptosis of target cells by mediating the passage and uptake of cytotoxic granzymes. Facilitates the delivery of cationic cargo protein, while anionic or neural proteins are not delivered efficiently. Perforin pores allow the release of mature caspase-7 (CASP7) into the extracellular milieu (By similarity).
Synonyms: P1; PFP; HPLH2
Tractability: Small molecule: a high-quality ligand is known; it belongs to a druggable protein family. Antibody: UniProt places it where antibodies can reach, with high confidence; its Gene Ontology location is reachable by antibodies, with high confidence; UniProt predicts a signal peptide or a membrane-spanning region. PROTAC: its protein half-life has been measured; a small molecule that binds it is known.
Target class: Ion channel; Other ion channel; Pore-forming toxins (proteins and peptides)
Gene: Protein-coding gene on chromosome 10 (70,596,401 to 70,602,759, reverse strand). Ensembl gene ENSG00000180644.
Subcellular location: Cytolytic granule; Secreted; Cell membrane; Endosome lumen
Subcellular location (Human Protein Atlas): Cytosol
Pathways (Reactome):
Disease: Nuclear events stimulated by ALK signaling in cancer
Gene Ontology:
Molecular function: identical protein binding; protein binding; wide pore channel activity; calcium ion binding; pore-forming activity
Biological process: granzyme-mediated programmed cell death signaling pathway; immunological synapse formation; protein homooligomerization; protein import; protein transmembrane transport; apoptotic process; cellular defense response; defense response to tumor cell; defense response to virus; immune response to tumor cell; protein secretion; T cell mediated cytotoxicity; defense response; immune system process; leukocyte mediated cytotoxicity
Cellular component: cytolytic granule; endosome lumen; membrane; plasma membrane; cytolytic granule lumen; immunological synapse; cytoplasmic vesicle; extracellular region
Genetic constraint (gnomAD): Loss-of-function variants: 11 observed, 12.63 expected, observed/expected ratio (o/e) 0.87, 90% interval 0.55 to 1.44. The upper end of that interval is the gene's LOEUF score, 1.44, which puts it in group 5 of 6, group 1 being the genes least tolerant of losing a copy. Missense variants: 729 observed, 782.21 expected, observed/expected ratio (o/e) 0.93, 90% interval 0.88 to 0.99. Synonymous variants: 314 observed, 341.61 expected, observed/expected ratio (o/e) 0.92, 90% interval 0.84 to 1.01.
Gene-disease validity (ClinGen):
ClinGen rates the evidence that PRF1 causes each of these diseases.
familial hemophagocytic lymphohistiocytosis 2 (autosomal recessive): Definitive.
Homologues: Orthologues: chimpanzee PRF1 (99% identical), macaque PRF1 (95% identical), rabbit PRF1 (78% identical), pig PRF1 (77% identical), dog PRF1 (75% identical), guinea pig PRF1 (73% identical), rat Prf1 (69% identical), mouse Prf1 (68% identical), zebrafish prf1.2 (38% identical), zebrafish prf1.7 (38% identical), tropical clawed frog prf1 (37% identical), zebrafish prf1.8 (36% identical), and 1 more. Paralogues in human: C6 (20% identical), C7 (18% identical), C8A (16% identical), CSMD1 (16% identical), C8B (16% identical), CSMD3 (15% identical), CSMD2 (15% identical), CFH (15% identical), SVEP1 (13% identical), PAPPA (13% identical), PAPPA2 (12% identical), C9 (12% identical), and 27 more.
Diseases named in the same sentence as PRF1 in open-access papers:
PRF1 is named in the same sentence as 209 diseases in open-access papers, as found by Europe PMC text mining. Sharing a sentence is not in itself a finding about the gene and the disease. The quoted sentences say what the papers report.
COVID-19 (27 papers, 2020 to 2026). A disease caused by infection with severe acute respiratory syndrome coronavirus 2. "The PRF1 rs885822 G/A presents a 56.8% for the wild G allele in the COVID-19 group, and this frequency is almost twice that observed in two databases." (PMID 36430210, 2022). "Furthermore, PRF1 rs350947132 was associated with increased immune tissue expression for perforin in the COVID-19 group." (PMID 36016321, 2022). "It has been reported that PRF1 and GZMB expression in CD8+ T cells increases during COVID-19 progression, potentially causing host cell damage during viral clearance." (PMID 38238762, 2024). "COVID-19 patients with encephalopathy had significant overexpression of various cytotoxic genes, including PRF1, GZMK, GZMA, GZMB, GNLY, and CST7." (PMID 37848421, 2023). "In the patients with moderate COVID-19, CD8+ TTE cells showed higher expression of IFNG, TNF, CCL5, PRF1, GZMB, and GZMA, together with genes encoding cytotoxic receptors (KLRB1, KLRC1, and KLRD1) in comparison with severe cases." (PMID 36119105, 2022). "Analysis of NK cell transcriptomic signatures furthermore confirmed that the increased expression of cytotoxic marker PRF1 and repair marker DDIT4 in NK cells was associated with recovered COVID-19 patients." (PMID 34975340, 2022). "These perforin-mediated cytolytic pathway heterozygous pHLH gene mutations (e.g., PRF1, UNC13D, AP3B1) have been reported in some cases of severe COVID-19 with HLH features." (PMID 35207437, 2022). "Within the first week of the disease, we found significantly increased gene expression of cytotoxic protein PRF1 in COVID-19 patients compared to healthy controls." (PMID 34945761, 2021). "PRF1 rs885822 G/A increases heterozygous genotype (GA) in COVID-19 vs. CONTROL groups." (PMID 36016321, 2022). "Therefore, whether the postvaccination upregulation of KLRD1 expression can confer protection by promoting the expressions of GZMB and PRF1, and whether KLRD1 expression is related to COVID-19 susceptibility needs to be clarified." (PMID 37654490, 2023). "COVID-19 group demonstrated significantly increased tissue immunoexpression of Arginase-1 and IL-4 (p = 0.002 and p < 0.0001, respectively) and increased number of Perforin-1+ (p = 0.009), CD4+ (p = 0.009), CD68+ (p = 0.013), CD138+ (p < 0.0001) cells in comparison to the H1N1 group." (PMID 36430210, 2022). "PRF1+ CD4+ T cell subsets have been detected in settings such as chronic infections, malignancies, and COVID-19." (PMID 41328434, 2025). "Specifically, compared to healthy controls, genes marking effector and cytotoxic CD8 T cell profiles (GZMB, NKG7, GZMH, PRF1, and CCL5) were upregulated in severe dengue and downregulated in severe COVID-19." (PMID 38294906, 2024). "Similar to GZMA, PRF1, GZMK and GZMB in T cells, significant increases in CASP3 were also present in COVID-19 patients with encephalopathy, and the highest expression of this gene was observed in acute necrotizing encephalopathy patients." (PMID 37848421, 2023). "We found that NKG7, IL32, GZMA, PRF1, CST7, GZMH, and CCL5 were among the top DEG downregulated in CD3+ upon nasal Foralumab treatment of COVID-19 subjects." (PMID 36881624, 2023). "Network pharmacology analyses identified 6 potential targets (IL6, DPP4, MIF, PRF1, SERPING1, and SLC6A4) for emetine in anti-LUAD/COVID-19." (PMID 35733175, 2022).
COVID-19 (continued). "Higher mRNA expression of PRF1 (p = 0.05) and lower mRNA expression of FASL (p = 0.05) at the fifth day of the disease were found in COVID-19 patients compared to healthy controls." (PMID 34945761, 2021). "In this study, we analyzed the gene expression pattern of cytotoxic proteins (PRF1, GZMB, GNLY, GZMA, GZMK), cytokine (IFN-γ), and apoptotic protein (FASL) in CD8+ T cells from the peripheral blood of COVID-19 patients." (PMID 34945761, 2021). "mRNA expression of PRF1 and IFN-γ was significantly downregulated in the first week of the disease in COVID-19 patients who progressed after the tenth day of illness to moderate and severe compared to patients with mild symptoms after the tenth day of illness." (PMID 34945761, 2021). "Indeed, NK cells and CD8+ T cells in BAL fluid from COVID-19 patients displayed increased transcript expression levels of GZMA, GZMB, and PRF1 even in patients with moderate disease." (PMID 35371005, 2022). "TH1-like cells from patients with mild COVID-19 exhibited a TH1 polarization state, characterized by upregulation of effector marker genes (PDCD1, CCL5, CXCR2, CCR2, GZMA/B, NKG7, PRF1, IFNG, and CCL4) and genes involved in effector function such as CXCR4, CXCL2, ANXA1, SOCS2 and LTB." (PMID 36119105, 2022). "In addition, we evaluated the potential bindings of emetine with the LUAD/COVID-19 targets (SLC6A4, MIF, DPP4, PRF1, SERPING1, and IL6)." (PMID 35733175, 2022). "When we correlated our findings with the outcome of COVID-19, there was a significant decrease in the expression of PRF1 and IFN-γ in CD8+ T cells in patients who developed moderate and severe COVID-19 compared to those who remained in the mild group after the tenth day of illness." (PMID 34945761, 2021). "Interestingly, decreased expression of both PRF1 and GZMB hub-high traffic genes in severe COVID-19 patients lead to dysfunction of NK cells cytotoxicity, indicating that both genes are essential for NK cells activity." (PMID 34975885, 2021). "However, a trend of higher mRNA expression of cytotoxic protein PRF1 and GZMB in COVID-19 patients at the fifth day of the disease was noticed." (PMID 34945761, 2021). "Other studies also reported increased PRF1, GNLY, soluble Fas, and GZMB in COVID-19 patients." (PMID 34945761, 2021). "mRNA expression of PRF1 (p < 0.001) and IFN-γ (p < 0.001) was significantly downregulated in the first week of disease in COVID-19 patients who progressed to moderate and severe forms after the first week, compared to patients with mild symptoms during the entire disease course." (PMID 34945761, 2021).
melanoma (26 papers, 2017 to 2026). A malignant, usually aggressive tumor composed of atypical, neoplastic melanocytes. "Downregulation of granzyme B (Gzmb), Perforin (Prf1) were observed in Prdm1-deficient NK cells, implying decreased anti-tumor ability, which was consistent with increased melanoma metastasis in Prdm1 cko mice." (PMID 39133873, 2024). "Expression of Ifng, Gzmb and Prf1 was elevated in B16 melanoma and NBL tumors excised from Cbx3/HP1γ-deficient mice compared to controls or Cbx3/HP1γTg animals." (PMID 34721405, 2021). "PRF1, which served as a definite marker of the killing ability of immune cells, is associated with better survival in multiple cancers, such as bladder cancer, melanoma, and head and neck squamous cell carcinoma." (PMID 37153540, 2023). "Genetic ablation of Prf1 in Cbx3/HP1γ-deficient animals led to uncontrolled B16 melanoma growth and decreased TUNEL positivity indicative of reduced tumor-cell apoptosis while NBL tumor burden was incompletely inhibited and tumor-cell death was readily detected." (PMID 34721405, 2021). "Mi-2β mRNA levels negatively correlated with both GZMB and PRF1 mRNA expression (p < 0.01) in melanoma." (PMID 38461299, 2024). "Prf1 and Gzmb levels in melanoma tumors from control and compound mutant mice as well as those treated with Cbx3-Il21r- or Il21r-deficient CD8+ effector T cells were low compared to Cbx3/HP1γ-deficient mice." (PMID 34721405, 2021). "PRF1 might be related to better survival in multiple cancers, including melanoma, bladder cancer, head and neck squamous cell carcinoma, and ovarian cancer." (PMID 40761790, 2025). "In agreement, a positive correlation between CD8+ T‐cell reactivity markers such as CD8A (coding gene for CD8), PRF1 (as Perforin), GZMB (coding gene for Granzyme B) and ERRα was observed, as indicated by co‐expression analyses in different melanoma databases." (PMID 39888245, 2025). "Next, to identify the role of Mi-2β in the immune response in melanoma, the correlation between Mi-2β and GZMB or PRF1 was analyzed." (PMID 38461299, 2024). "NLRC5 expression was significantly positively associated with both CYT score and the expression of PRF1 and GZMA in all four melanoma datasets." (PMID 34307322, 2021). "All phenotypic and functional markers of T cells—CD3E, CD4, CD8B, FOXP3, GZMB, PRF1 and TBX21—were expressed at higher levels in melanoma patients with high ETV7 expression." (PMID 33424867, 2020). "Accordingly, we observed the expression of Prf1 and Gzmb, encoding the CD8 T cell derived cytotoxic perforin 1 and granzyme B, only in NRF2 knockout, but not in control melanomas." (PMID 32978520, 2020). "The expressions of CD8A, GZMA, GZMK and PRF1 genes in the NOS1-high-expression group were significantly lower than those in the NOS1-low-expression group, indicating that NOS1 might play an immunoregulatory role only in “cold” melanoma." (PMID 41535256, 2026). "Moreover, CD8A and PRF1 expression inversely correlate with LDH‐A, thereby corroborating that a lactate‐rich environment negatively impacts on the CD8‐mediated antitumour immunity in melanoma." (PMID 39888245, 2025). "And the negative correlation between 6 ICD-related genes (CD8A, PRF1, IFNG, CXCR3, TNF, CD8B) and risk score and the protective function of these 6 genes in SKCM indicates that drugs targeting these genes may be a novel treatment method in melanoma." (PMID 36211436, 2022). "Leveraging The Cancer Genome Atlas (TCGA) datasets, we investigated NR4A1 expression in melanoma patients and identified a negative correlation between NR4A1 and genes involved in the antitumor immune responses, including IFNγ (interferon γ), GZMB (granzyme B), and PRF1 (perforin)." (PMID 38334978, 2024).
hemophagocytic lymphohistiocytosis (23 papers, 2012 to 2026). "Herein, we presented 2 cases of a familial hemophagocytic syndrome caused by PRF1 gene mutation in 1 family with central nervous injury as the first symptom and searched relevant literature for clinical analysis of its pathogenic characteristics." (PMID 37390248, 2023). "Reanalysis found a homozygous variant in the PRF1 gene, which is associated with hemophagocytic lymphohistiocytosis (HLH) type 2." (PMID 32963807, 2020). "Patients 22 and 29 were both identified to have homozygous variants in PRF1 (NM_005041) associated with hemophagocytic lymphohistiocytosis (HLH)." (PMID 31664448, 2019). "In patient 012 affected with hemophagocytic lymphohistiocytosis and marked reduction of perforin expression in NK cells, we identified two heterozygous mutations in PRF1 that were located in the same allele as shown by Sanger sequencing." (PMID 27872624, 2016). "On the other hand, the familial or primary form of hemophagocytic lymphohistiocytosis (fHLH/pHLH) occurs due to autosomal recessive defects in genes (PRF1; UNC13D; STX11; STXBP2) encoding proteins involved in cytotoxic granule exocytosis of NK-induced apoptosis." (PMID 36016321, 2022). "Mutations in genes of the cytotoxic pathway (e.g. PRF1) can lead to hemophagocytic lymphohistiocytosis (HLH) after an infectious trigger, terming these diseases collectively as hemophagocytic syndromes." (PMID 25339095, 2014). "Six days after MCMV infection, Prf1 KO mice were affected by multiple histologic changes consistent with hemophagocytic syndrome." (PMID 22891066, 2012). "Mutations in PRF1, STXBP2, and UNC13D are associated with hemophagocytic lymphohistiocytosis." (PMID 38502913, 2024).
autoimmune disease (16 papers, 2013 to 2025). A disorder resulting from loss of function or tissue destruction of an organ or multiple organs, arising from humoral or cellular immune responses of the individual to their own tissue constituents. "PRF1 mutations disrupt cytotoxic lymphocyte function and lead to chronic immune activation, thereby contributing to the pathogenesis of autoimmune disease." (PMID 40993545, 2025). "Almost all variants identified (ZNF365, TNFSF4, NAB1, IKZF4-ERBB3, CTSC, DENND1B, SIRPG, and PRF1) are the same or strongly linked with markers associated with other autoimmune diseases." (PMID 37188663, 2023). "Monoallelic PRF1 mutation increases the risk of autoimmune diseases, and biallelic PRF1 mutation causes familial hemophagocytic lymphohistiocytosis-2." (PMID 38149249, 2023). "By contrast, the OPN and PRF1 variants were involved in development of several other autoimmune diseases." (PMID 23840885, 2013). "All but four out of 26 red group signals (PRF1, CTRB2, MEG3 and RNLS) were associated with other autoimmune diseases found in the Open Targets Genetics portal." (PMID 39749473, 2025). "While primary HLH typically manifests in children due to mutations in genes such as PRF1, UNC13D, STX11 and STXBP2, secondary HLH is more common in adults and is usually triggered by infections, cancers, autoimmune disorders or immunosuppressive therapy." (PMID 41181728, 2025). "Our analysis indicated that both subsets showed enhanced cytotoxicity, with sustained increases in expression and chromatin accessibility of key cytotoxic genes such as GZMB, FGFBP2, CTSW, PRF1, which are crucial in other autoimmune disorders." (PMID 39365735, 2024). "Most genes were related to autoimmune diseases like ATM, NCF1, MCM4, FCN3, and DOCK8 or autoinflammatory diseases associated with the release of IFN-gamma, such as PRF1, NOD2, and MEF." (PMID 37588055, 2023). "Prf1−/− × PD-1−/− thymocyte recipients all developed autoimmune disease between days 13 and 21 post-transfer, while the PD-1−/− thymocyte recipients had a relatively slightly delayed course of disease (p = 0.01)." (PMID 29416537, 2018). "DNA hypomethylation exists in numerous autoimmune diseases, which can promote the overexpression of methylation-sensitive genes, such as: PRF1, IFN-γ, CD7026." (PMID 29748604, 2018). "Cytotoxic CD8 T cells, including PRF1 + and GZMK + cells, are known to be involved in the pathogenesis of autoimmune diseases and viral myocarditis." (PMID 41510228, 2025).